AHR (aryl hydrocarbon receptor)
Diseases named in the same sentence as AHR in open-access papers (continued):
Sharing a sentence is not in itself a finding about the gene and the disease.
rheumatoid arthritis (59 papers, 2010 to 2026). A chronic, systemic autoimmune disorder characterized by inflammation in the synovial membranes and articular surfaces. "Environmental factors, especially polycyclic aromatic hydrocarbons, are implicated in the pathogenesis of rheumatoid arthritis; hence, the role of AhR in this pathogenesis is of interest." (PMID 35743162, 2022). "Of note, in different cells implicated in rheumatoid arthritis, the effects of AhR activation are opposite." (PMID 35743162, 2022). "In systemic autoimmune disorders such as rheumatoid arthritis, the immunosuppressive function of regulatory B cells has been linked to the AhR transcriptional program." (PMID 35804761, 2022). "The authors argue that tobacco smoke is a well-known environmental risk factor for development of rheumatoid arthritis since it contains AhR agonists, such as 2,3,7,8-tetrachlorodibenzo-p-dioxin, 3-methyl cholanthrene, and benzo[a]pyrene." (PMID 27197967, 2016). "One study analyzing B cell-specific AhR-deficient mice demonstrated that AhR signaling in regulatory B cells (Bregs) induces IL-10 secretion, thereby, dampening inflammatory Th1 and Th17 responses in a murine rheumatoid arthritis model." (PMID 36875083, 2023). "Interestingly it has been shown that 2,3,7,8-tetrachlorodibenzo-p-dioxin (TCDD) and 3-methylcholanthrene (3-MC), two components derived from cigarette smoke and known environmental risk factors for rheumatoid arthritis, act as exogenous ligands for AHR." (PMID 24454481, 2013). "The alteration of AHR expression induced by periodontitis may have significant implications in the pathophysiology of systemic disorders linked to periodontitis, including Alzheimer’s disease, diabetes, and rheumatoid arthritis." (PMID 39575260, 2024). "Rheumatoid arthritis (RA) development is strongly associated with cigarette smoke exposure, which activates the aryl hydrocarbon receptor (AhR) as a trigger for Th17 inflammatory pathways." (PMID 34200499, 2021). "Lactobacillus produces 3-indoleacrylic acid, which activates AHR, alleviates intestinal inflammation, and mitigates rheumatoid arthritis." (PMID 40251524, 2025). "Lactobacillus can produce Trp metabolites, including 3-indoleacrylic acid, which ameliorates intestinal inflammation and injury by binding to and activating AHR, thereby alleviating rheumatoid arthritis." (PMID 40251524, 2025). "AhR, an important immunomodulator, also has strong potential for therapeutic intervention in multiple inflammatory diseases such as sclerosis and rheumatoid arthritis." (PMID 38635505, 2024). "Keywords include gut microbiota, rheumatoid arthritis, chain fatty acids, segmented filamentous bacteria, aryl-hydrocarbon receptor, etc." (PMID 36699603, 2022). "The most significant AhR activity has been shown for butyrate, which has led to the suggestion of this metabolite for reducing systemic autoimmune disorders such as rheumatoid arthritis." (PMID 35804761, 2022). "AhR, a major immunomodulator, is expressed in various cells (T and B cells, natural killers, macrophages, and dendritic cells) involved in rheumatoid arthritis." (PMID 35743162, 2022). "Currently, there are many review articles describing the role of AhR signaling in inflammatory diseases, e.g., atherosclerosis, neurodegenerative diseases, rheumatoid arthritis, and chronic infections." (PMID 35987825, 2022). "Accordingly, there is evidence that an increase in AhR signaling occurs in many age-related diseases, such as atherosclerosis, cancers, and rheumatoid arthritis." (PMID 35987825, 2022). "Recently, it has been shown that human umbilical mesenchymal stem cells (hUC-MSCs) treat rheumatoid arthritis (RA) by regulating the interaction between gut microbiota and host immunity through the aryl hydrocarbon receptor (AhR)." (PMID 34925385, 2021). "The anti-inflammatory drug leflunomide, approved for the treatment of rheumatoid arthritis in 1998, has been shown to be an AhR agonist." (PMID 33451095, 2021).
rheumatoid arthritis (continued). "IAld I3AA inhibited the expression of IL1b and IL6 in an AhR dependent manner, whereas I3AA showed AhR-independent anti-angiogenic activity in cell-based models of rheumatoid arthritis." (PMID 34639632, 2021). "AhR expression is also essential for the differentiation and activation of Th17 cells in the pathogenesis of rheumatoid arthritis." (PMID 32977499, 2020). "AhR is seeing a resurgence of interest in a range of other disease indications and early phase clinical trials are underway with AhR antagonists in oncology indications and rheumatoid arthritis." (PMID 32597486, 2020). "There is a lot of evidence that AhR plays an important role in rheumatoid arthritis (RA) pathogenesis." (PMID 32899152, 2020). "The connection between HQ exposure and AhR to rheumatoid arthritis was recently tested in mice and rats exposed to HQ by inhalation following an experimental design of low-dose exposures." (PMID 32977499, 2020). "Solid experimental and clinical data show a correlation between exposure to cigarette smoking and the induction and aggravation of rheumatoid arthritis; there is also increased AhR expression in the synovial membrane of smokers." (PMID 32977499, 2020). "For example, Kobayashi and colleagues have shown that environmental exposure to TCDD, through binding to AhR, exacerbates rheumatoid arthritis pathophysiology via stimulation of the NF-κB and ERK signaling pathways." (PMID 30030472, 2018). "This is supported by the recent data of Nguyen and co-authors which showed that AhR mediates the immune regulatory mechanism of rheumatoid arthritis." (PMID 27197967, 2016). "Evidence links aryl hydrocarbon receptor (AHR) activation to rheumatoid arthritis (RA) pathogenesis, although results are inconsistent." (PMID 26838552, 2016). "The objective of this study was to establish any effect of smoking on the inflammatory tissue lesions of rheumatoid arthritis via the AHR and IL-17A." (PMID 23036591, 2012). "In stage analysis, altered T cell and B cell signaling in rheumatoid arthritis, B cell development, aryl hydrocarbon receptor signaling, PXR/RXR activation, and LPS/IL-1 mediated inhibition of RXR function were among the top ten pathways." (PMID 22912720, 2012). "During a screen for molecules that activate the AhR, leflunomide, an immunomodulatory drug presently used in the clinic for the treatment of rheumatoid arthritis, was identified as an AhR agonist." (PMID 20957046, 2010). "Based on the AhR activation mechanism, IPyA plays a potential role as a preventative factor in modulating inflammatory responses in animal models of chronic colitis and rheumatoid arthritis." (PMID 39195540, 2024). "However, certain endogenous metabolites and natural ligands have been shown to relieve the severity of rheumatoid arthritis by activating the AHR." (PMID 39575260, 2024). "A more recent study of the same group indicates that AhR signaling induced by dietary SCFA butyrate supplementation favors the formation of Bregs during GC response and, thereby, alleviating inflammation in the cause of rheumatoid arthritis." (PMID 36875083, 2023). "Among them, semaphorine 4D seems to be involved not only in rheumatoid arthritis (RA) pathogenesis but also in AS immune dysregulation, being able to act through the aryl-hydrocarbon receptor AhR pathway, thus increasing TH17 response and inhibiting the TREG counterpart." (PMID 37047435, 2023). "Although much basic research has been conducted on the role of polycyclic aromatic hydrocarbon-activated AhR in rheumatoid arthritis, clinical studies on its effects on the mechanism of AhR signaling in rheumatoid arthritis are still lacking, and further research is needed." (PMID 35743162, 2022). "AhR plays a critical role in Th17 cell activation during the development of rheumatoid arthritis (RA)." (PMID 40182693, 2025). "AhR agonists with fewer adverse effects may be candidate therapeutics for rheumatoid arthritis." (PMID 35743162, 2022).
rheumatoid arthritis (continued). "AhR agonist leflunomide, which is used for the treatment of rheumatoid arthritis (RA), exhibits anti-inflammatory activity." (PMID 27012456, 2016). "Thus AhR targeted therapy is also potentially useful for rheumatoid arthritis." (PMID 24905409, 2014). "Thus, AHR may represent an interesting link between environmental factors and autoimmune development in regard to rheumatoid arthritis." (PMID 24454481, 2013). "This is consistent with the fact that LEF induces the AHR–ARNT interaction, thereby attenuating bone erosion in rheumatoid arthritis." (PMID 35073843, 2022). "Overall, our study is the first report that AhR negatively regulates human osteoclast differentiation and suggests that AhR could be good therapeutic molecule to prevent bone destruction in chronic inflammatory diseases such as rheumatoid arthritis (RA)." (PMID 34944003, 2021). "Furthermore, other reported AhR antagonists also upregulate utrophin, showing that this pathway, which is currently being explored in other clinical applications including oncology and rheumatoid arthritis, could also be exploited in future DMD therapies." (PMID 31755636, 2020). "This might be another milestone for the long way of developing AhR-directed therapeutic approaches for acute (e.g., SIRS/Sepsis) or chronic inflammatory diseases (e.g., chronic inflammatory bowel disease, rheumatoid arthritis, or allergies)." (PMID 35203386, 2022). "The AhR protein expression was up-regulated in the presence of TNF-α and smoking and exposure to TCDD enhanced rheumatoid arthritis (RA) inflammatory processes in synovial tissue from RA patients." (PMID 27520027, 2016).
COVID-19 (58 papers, 2020 to 2025). A disease caused by infection with severe acute respiratory syndrome coronavirus 2. "In COVID-19, AHR activation has been associated with impaired interferon signalling, altered ACE2 expression, and sustained viral proliferation." (PMID 40949107, 2025). "KA is implicated in deteriorating male COVID-19 patients through affecting the AhR, one of the master regulators of the immune-inflammatory response." (PMID 35840908, 2022). "Based on the available literature, it seems inevitable that activation of the IDO-Kyn-AhR pathway in COVID-19 patients should lead to bone and muscle loss, inducing significant musculoskeletal damage." (PMID 34621138, 2021). "Likewise, there is a controversial idea on the protective role of aryl hydrocarbon receptor (AhR), a xenobiotic receptor, in COVID-19 patients susceptible to aspergillosis." (PMID 34575758, 2021). "Finally, we found that the pharmacological inhibition of AHR suppressed the replication in vitro of one of the causative agents of the common cold, HCoV-229E, and the causative agent of the COVID-19 pandemic, SARS-CoV-2." (PMID 34446714, 2021). "During COVID-19, AHR activation contributes broadly to disease progression, modulating immune responses, vascular integrity, and neurological function." (PMID 40949107, 2025). "In relation to COVID-19, AHR activation drives immune suppression, systemic inflammation, and metabolic disturbances, intensifying disease severity." (PMID 40949107, 2025). "Several studies suggest that AhR selectively induces IDO2 expression, and recent findings from COVID-19 models highlight a potential IDO2-driven positive feedback loop sustaining AhR activation in severe disease." (PMID 40471422, 2025). "In the context of COVID-19, AHR represents a promising therapeutic target for modulating aberrant inflammatory responses." (PMID 40949107, 2025). "The activation of the AHR plays a pivotal role in modulating immune, inflammatory, and metabolic pathways during COVID-19, particularly in individuals with pre-existing comorbidities." (PMID 40949107, 2025). "Nevertheless, prolonged or excessive AHR activation poses risks, including immune suppression, viral persistence, and tissue fibrosis, concerns particularly relevant in long COVID-19." (PMID 40949107, 2025). "The aim of the study was the evaluation of the VDR and AhR pathways in the blood of COVID-19 patients with regard to the severity of disease." (PMID 38474725, 2024). "We observed an altered expression of AHR in patients with COVID-19, potentially influencing immune responses and recovery." (PMID 38932276, 2024). "Our investigation explored potential associations between gene expression of AHR, FFAR2, FXR, and TGR5, and COVID-19 outcomes in patients with MAFLD." (PMID 38932276, 2024). "In severe COVID-19 patients, the activation of AhR by IDO1-derived tryptophan metabolites acts as a biological defense mechanism." (PMID 39408347, 2024). "In line and accordance with this proviral role of AHR in COVID-19 infection, we found a 21.3-fold up-regulation of AHR observed in COVID-19 patients compared to controls." (PMID 38932276, 2024). "Recently, their popularity increased upon finding that AhR activation can be induced by infections with coronaviruses, like HCoV-229E (common cold) and SARS-CoV-2 (COVID-19), and that the use of AhR antagonists can boost antiviral immunity." (PMID 37958638, 2023). "We have already reported that the impaired tryptophan metabolism in patients with severe COVID-19 is associated with decreased expression of ACE2, AHR, CARD9 in the ileal mucosa." (PMID 39131552, 2023). "HLA-DRB3, CXCL13, PTPN22 and AHR were identified as genes that were commonly down-regulated in both COVID-19(+) TV and COVID-19(+) PU groups compared to the COVID-19(-) PU control group." (PMID 37026002, 2023).
COVID-19 (continued). "Together, these in vivo data strongly supported a role for AhR signaling in SARS-CoV-2 replication and pathogenesis and identified AhR antagonism as a candidate therapeutic approach for COVID-19." (PMID 37256962, 2023). "The major Kyn metabolite targeted by COVID-19 is kynurenic acid (KA), the Kyn metabolite with the greatest affinity for the aryl hydrocarbon receptor (AhR), which is also activated by COVID-19." (PMID 37486805, 2023). "Lactobacillus, which was proved to be remarkably decreased in COVID-19 patients, can produce the aryl hydrocarbon receptor (AhR) ligand-indole-3-aldehyde that promotes AhR-dependent IL22 transcription and improves resistance against mucosal inflammation." (PMID 38455085, 2023). "The mucosal gene expression analysis showed both AHR and the downstream IL-22 gene were decreased in critical COVID-19 group." (PMID 36035409, 2022). "In patients with severe COVID-19, activation of the kynurenine pathway by various cytokines, and tryptophan metabolites regulate immune responses through AhR and GPR35 activation." (PMID 35463998, 2022). "Lactobacillus, which was known to be significantly reduced in COVID-19 patients, can produce the aryl hydrocarbon receptor (AhR) ligand-indole-3-aldehyde that promotes AhR-dependent IL22 transcription and improves resistance to mucosal inflammation." (PMID 36033885, 2022). "In 2016, long before the COVID-19 outbreak, Rothhammer’s group described the involvement of AhR in the anti-inflammatory effect of IFN-Is in experimental models of CNS autoimmunity and in patients suffering from multiple sclerosis (MS)." (PMID 35203299, 2022). "Taken together, these data depict a framework where sufficient clues suggest the possible participation of AhR in the management of COVID-19 inflammation, thus indicating an additional therapeutic target for this disease." (PMID 35203299, 2022). "In conclusion, patients with critical COVID-19 have gastrointestinal inflammation potentially caused by impaired tryptophan metabolism due to decreased ACE2 expression and AhR pathway disruption." (PMID 36035409, 2022). "The expression of ACE2, AHR, and CARD9 was decreased in the ileum of the COVID-19 patients, and the expression of IL22, a cytokine regulated by aryl hydrocarbon receptor (AhR), was also decreased in the ileum of the COVID-19 patients." (PMID 36035409, 2022). "Current studies regarding the activation of the IDO-Kyn-AhR pathway in COVID-19 patients have opened up a new frontier for the scientific research community." (PMID 34621138, 2021). "In COVID-19 patients, AhR stimulation upregulates expression of mucins in alveolar epithelial cells, causing accumulation of alveolar mucus and leading to silent hypoxia formation, a unique feature of the disease." (PMID 34394108, 2021). "This possibility, however, does not detract from our observations in COVID-19 patients or from the potential of AhR as a therapeutic target in COVID-19." (PMID 34230210, 2021). "Here, we show that infection with different CoVs activates AHR signaling in vitro and also in COVID-19 patients." (PMID 34446714, 2021). "Recently, an increase in circulating KP metabolites was shown in COVID-19 patients supporting a role for enhanced AhR activation in response to SARS-CoV-2." (PMID 32957545, 2020). "A potential AhR activation by IFN-β is likely to be additive to that by COVID-19, if the two act by different mechanisms." (PMID 33063092, 2020). "A possible aberrant activation of AhR and IDO1 has been put forward to explain the symptomatology of COVID-19 patients, and a recent study identified AhR signaling as a common host response to infection by coronaviruses responsible for lung pathogenesis." (PMID 33322584, 2020). "Viral pathogens such as Zika virus (ZIKV) and Dengue virus (DENV) exploit AHR signalling to enhance replication and evade host defences, and emerging data suggest a similar mechanism in SARS-CoV-2 infection." (PMID 40949107, 2025).